TFRC (transferrin receptor)
Description:
Cellular uptake of iron occurs via receptor-mediated endocytosis of ligand-occupied transferrin receptor into specialized endosomes. Endosomal acidification leads to iron release. The apotransferrin-receptor complex is then recycled to the cell surface with a return to neutral pH and the concomitant loss of affinity of apotransferrin for its receptor. Transferrin receptor is necessary for development of erythrocytes and the nervous system (By similarity). A second ligand, the hereditary hemochromatosis protein HFE, competes for binding with transferrin for an overlapping C-terminal binding site. Positively regulates T and B cell proliferation through iron uptake. Acts as a lipid sensor that regulates mitochondrial fusion by regulating activation of the JNK pathway. When dietary levels of stearate (C18:0) are low, promotes activation of the JNK pathway, resulting in HUWE1-mediated ubiquitination and subsequent degradation of the mitofusin MFN2 and inhibition of mitochondrial fusion. When dietary levels of stearate (C18:0) are high, TFRC stearoylation inhibits activation of the JNK pathway and thus degradation of the mitofusin MFN2. Mediates uptake of NICOL1 into fibroblasts where it may regulate extracellular matrix production (By similarity). (Microbial infection) Acts as a receptor for new-world arenaviruses: Guanarito, Junin and Machupo virus. (Microbial infection) Acts as a host entry factor for rabies virus that hijacks the endocytosis of TFRC to enter cells. (Microbial infection) Acts as a host entry factor for SARS-CoV, MERS-CoV and SARS-CoV-2 viruses that hijack the endocytosis of TFRC to enter cells. (Microbial infection) Acts as a receptor for Plasmodium vivax.
Synonyms: TR; TfR; TfR1; Trfr; CD71; p90; IMD46; T9
Tractability: Small molecule: it has a high-quality binding pocket. Antibody: a drug acting on it is in phase 1 trials; UniProt places it where antibodies can reach, with high confidence; its Gene Ontology location is reachable by antibodies, with high confidence; UniProt predicts a signal peptide or a membrane-spanning region. PROTAC: ubiquitination databases record sites on it; its protein half-life has been measured. Other modalities: a drug acting on it is in phase 2 or 3 trials.
Target class: Membrane receptor
Gene: Protein-coding gene on chromosome 3 (196,012,511 to 196,082,162, reverse strand). Ensembl gene ENSG00000072274.
Subcellular location: Cell membrane; Melanosome; Secreted (Transferrin receptor protein 1, serum form)
Subcellular location (Human Protein Atlas): Endosomes; Lysosomes; Predicted to be secreted
Pathways (Reactome):
Signal Transduction: CDC42 GTPase cycle; RAC1 GTPase cycle; RAC2 GTPase cycle; RAC3 GTPase cycle; RHOA GTPase cycle; RHOB GTPase cycle; RHOC GTPase cycle; RHOG GTPase cycle; RHOH GTPase cycle; RHOJ GTPase cycle; RHOQ GTPase cycle; RND1 GTPase cycle; RND2 GTPase cycle
Vesicle-mediated transport: Cargo recognition for clathrin-mediated endocytosis; Clathrin-mediated endocytosis; Golgi Associated Vesicle Biogenesis
Developmental Biology: Differentiation of Keratinocytes in Interfollicular Epidermis in Mammalian Skin
Transport of small molecules: Transferrin endocytosis and recycling
Gene Ontology:
Molecular function: double-stranded RNA binding; identical protein binding; protein binding; protein homodimerization activity; protein kinase binding; protein-containing complex binding; RNA binding; transferrin receptor activity; Hsp70 protein binding; protein-folding chaperone binding
Biological process: cell surface receptor signaling pathway; cellular response to xenobiotic stimulus; intracellular signal transduction; iron ion transport; multicellular organismal-level iron ion homeostasis; negative regulation of apoptotic process; negative regulation of mitochondrial fusion; positive regulation of B cell proliferation; positive regulation of canonical NF-kappaB signal transduction; positive regulation of gene expression; positive regulation of isotype switching; positive regulation of protein localization to nucleus; positive regulation of protein-containing complex assembly; positive regulation of T cell proliferation; receptor internalization; receptor-mediated endocytosis; regulation of cell growth; regulation of cell population proliferation; transferrin transport; intracellular iron ion homeostasis; transport across blood-brain barrier; acute-phase response; osteoclast differentiation; regulation of postsynaptic membrane neurotransmitter receptor levels; response to copper ion; and 5 more
Cellular component: basolateral plasma membrane; blood microparticle; cell surface; clathrin-coated pit; cytoplasmic vesicle; endosome; endosome membrane; external side of plasma membrane; extracellular exosome; extracellular region; extracellular vesicle; HFE-transferrin receptor complex; lysosome; melanosome; perinuclear region of cytoplasm; plasma membrane; recycling endosome; clathrin-coated endocytic vesicle membrane; membrane; early endosome; glutamatergic synapse; postsynapse; postsynaptic recycling endosome membrane; recycling endosome membrane
Genetic constraint (gnomAD): Loss-of-function variants: 28 observed, 78.47 expected, observed/expected ratio (o/e) 0.36, 90% interval 0.26 to 0.49. The upper end of that interval is the gene's LOEUF score, 0.49, which puts it in group 2 of 6, group 1 being the genes least tolerant of losing a copy. Missense variants: 753 observed, 887.05 expected, observed/expected ratio (o/e) 0.85, 90% interval 0.8 to 0.9. Synonymous variants: 339 observed, 322.36 expected, observed/expected ratio (o/e) 1.05, 90% interval 0.96 to 1.15.
Gene-disease validity (ClinGen):
ClinGen rates the evidence that TFRC causes each of these diseases.
TFRC-related combined immunodeficiency (autosomal recessive): Definitive.
Homologues: Orthologues: chimpanzee TFRC (99% identical), macaque TFRC (95% identical), rabbit TFRC (82% identical), dog TFRC (79% identical), pig TFRC (78% identical), guinea pig TFRC (77% identical), rat Tfrc (77% identical), mouse Tfrc (77% identical), tropical clawed frog tfrc (49% identical), zebrafish tfr1a (44% identical), zebrafish tfr1b (39% identical). Paralogues in human: TFR2 (43% identical), FOLH1 (24% identical), NAALAD2 (24% identical), NAALADL1 (23% identical), NAALADL2 (19% identical).
Diseases named in the same sentence as TFRC in open-access papers:
TFRC is named in the same sentence as 474 diseases in open-access papers, as found by Europe PMC text mining. Sharing a sentence is not in itself a finding about the gene and the disease. The quoted sentences say what the papers report.
iron deficiency (482 papers, 2003 to 2026). "Iron deficiency increases the density of transferrin receptors (TfR1), allowing greater intracellular entry of aluminium, which is osteotoxic even at low doses and contributes to impaired osteoblast function and ferroptotic cell injury." (PMID 41496457, 2026). "Transferrin receptor levels increase during iron deficiency, a frequent comorbidity found in patients with ACS." (PMID 40503438, 2025). "The measurement of soluble transferrin receptor can help differentiate between anemia of chronic disease and iron deficiency, where soluble transferrin receptor levels are low or normal in anemia of chronic disease and high in iron deficiency." (PMID 40002904, 2025). "This study developed an FTH1 expression system regulated by chimeric elements, leveraging the mechanism whereby FTH1 overexpression induces intracellular iron deficiency to activate upregulation of transferrin receptor (TfR) expression." (PMID 40723232, 2025). "Transferrin receptor-1 is essential for cellular iron uptake, and its cleaved form in the blood, sTfR1, is primarily established as a marker of erythropoietic activity and iron-deficient anemia." (PMID 40659927, 2025). "Recent research has explored the combined use of low hepcidin and elevated soluble transferrin receptor (sTfR) levels as an alternative approach for diagnosing iron deficiency in heart failure." (PMID 40869365, 2025). "Elevated maternal soluble transferrin receptor (sTfR) levels (>3.7 mg/L), indicative of iron deficiency, were associated with reduced B. infantis colonization in infants." (PMID 39855335, 2025). "Other clinical tests, such as serum ferritin, transferrin saturation, soluble transferrin receptor, or C-reactive protein, proved to be useful adjunctive tests to assist in the diagnosis of iron deficiency." (PMID 40704327, 2025). "In other instances, the serum transferrin receptor (TfR) has been employed in assessing iron-deficient anaemia (IDA)." (PMID 40890373, 2025). "Another parameter, the concentration of soluble transferrin receptors (sTfR) in circulation, has also been used to diagnose iron deficiency." (PMID 40497187, 2025). "They discovered a compelling association between elevated levels of soluble transferrin receptor (sTfR), a marker of iron deficiency or increased erythropoiesis, and the development of a range of organ manifestations, including pulmonary complications." (PMID 40564204, 2025). "Conventionally, iron deficiency diagnosis is based on determining ferritin, transferrin saturation, and soluble transferrin receptor, but these biomarkers are strongly influenced by inflammation and infection." (PMID 38435983, 2024). "Evidence suggests hepcidin is a key regulator of caveolae formation in brain endothelial cells, with its deletion resulting in iron deficiency and subsequent activation of the transferrin receptor system." (PMID 39107268, 2024). "For example, in patients with iron-deficiency anemia, the expression level of TFRC is usually high, whereas in patients with iron overload, the expression is low." (PMID 39199933, 2024). "Iron deficiency (ID) was defined as total body iron (calculated from serum ferritin and transferrin receptor using Cook’s equation) < 0 mg/kg and anemia as hemoglobin < 11 g/dL." (PMID 39255312, 2024). "Soluble transferrin receptor (sTfR) is an extracellular fragment of the transferrin receptor whose serum concentration increases in a state of functional iron deficiency." (PMID 39519457, 2024). "For instance, the soluble transferrin receptor exhibits an inverse relationship with tissue iron availability and thus is elevated in iron deficiency states." (PMID 39507475, 2024). "The analysis of a soluble transferrin receptor (sTfR) concentration in blood is utilized for investigating iron deficiency anemia and assessing iron the functional status." (PMID 38612266, 2024).
iron deficiency (continued). "The data matched other findings that reported that Hgb, iron concentration, SF, and soluble transferrin receptor (sTfR) were the most commonly utilized markers of iron deficiency in clinical practice." (PMID 38102707, 2023). "Increased serum levels of the soluble transferrin receptor (s-TfR) are suspected in an iron deficiency condition." (PMID 37189944, 2023). "The determination of soluble transferrin receptor (sTfR), which is the plasma-soluble form of the transferrin receptor and an indicator of tissue iron deficiency, is helpful in differentiating between ACD and IDA." (PMID 38139169, 2023). "Recent studies have shown that patients with a point mutation in the transferrin receptor have combined B and T cell immunodeficiency characterized by iron deficiency." (PMID 36831233, 2023). "The serum transferrin receptor to ferritin concentration ratio (sTfR:SF) can be used to estimate iron status in individuals with iron deficiency, normal iron balance, and increased iron stores." (PMID 37061792, 2023). "Soluble transferrin receptor has been identified as another micronutrient status indicator as it measures iron deficiency." (PMID 37976323, 2023). "Soluble transferrin receptor (sTfr) reflects iron utilization in the body and can better describe functional or absolute iron deficiency in the body than ferritin and transferrin saturation in clinical practice." (PMID 37215140, 2023). "Iron deficiency orchestrates iron regulation through the iron regulatory proteins (IRPs) which bind to the 3′ UTR of transferrin receptor (TfR1) or 5′ UTR of ferritin mRNA, leading to increased iron uptake or decreased iron storage, respectively." (PMID 37513518, 2023). "The included studies assessed secondary outcomes, including changes in mean serum ferritin level, serum transferrin receptor, serum iron, and improvement in iron deficiency anemia." (PMID 37069552, 2023). "In inflammatory condition, testing for both transferrin receptor and ferritin is a more reliable method to identify related iron deficiencies." (PMID 36778054, 2023). "In most clinical practices, the most commonly utilized markers of iron deficiency were haemoglobin (Hgb), iron concentration, serum ferritin (SF), and soluble transferrin receptor (sTfR), the levels of which efficiently reflect intracellular iron stores." (PMID 38102707, 2023). "Some blood subsamples measured additional indicators (ferritin, serum transferrin receptor, etc.)to enhance results’ validity for iron deficiency anemia." (PMID 37957706, 2023). "We assessed hemoglobin (a biomarker of anemia) with a hemoglobinometer and soluble transferrin receptor (a biomarker of iron deficiency) and C-reactive protein (a biomarker of inflammation) in dried blood spots via enzyme immunoassay." (PMID 37315072, 2023). "Soluble transferrin receptor is the plasma-soluble form of the transferrin receptor and is an indicator of tissue iron deficiency." (PMID 38139169, 2023). "A rare homozygous mutation of p.Y20H in TFRC was first reported in two pedigrees to cause low MCV and combined immunodeficiency by impaired TFRC internalization and consequent intracellular iron deficiency." (PMID 37646182, 2023). "Meanwhile, IRPs can stabilize mRNA by binding to the IRE in the 3’-UTR of divalent metal transporter 1 (DMT1) and transferrin receptor 1 (TfR1), which promotes iron uptake and ultimately alleviates iron deficiency." (PMID 36978814, 2023). "Based on the findings, FKN enhances the expression of iron metabolism-related genes in iron deficiency and modifies the iron uptake via transferrin receptor 1 and divalent metal transporter-1, and iron release via ferroportin." (PMID 37373063, 2023). "A recent study showed that, unexpectedly, mice with adipocyte-specific deletion of transferrin receptor-1 leading to local iron deficiency had impaired absorption of lipids from the intestine." (PMID 37029208, 2023).
iron deficiency (continued). "In our population, the prevalence of iron deficiency was quite low, with only 14% of women with low iron stores (ferritin < 30 μg/L) and <5% with iron deficiency (ferritin < 12 μg/L or transferrin receptor > 8.3 mg/L)." (PMID 36925072, 2023). "In CKD, kidney macrophages exhibited depletion of labile iron pool (LIP) and induction of transferrin receptor 1, indicating intracellular iron deficiency." (PMID 36394951, 2023). "Decreased transferrin saturation or increased soluble transferrin receptor (sTfR) portrays the second stage of iron deficiency, reflecting reduced erythropoiesis." (PMID 35807896, 2022). "Post burn M-CSF blockade led to further deterioration in reticulocyte indices of iron deficiency, % Low CH and % Hypo, and augmented a burn induced elevation of erythroid transferrin receptor which can be a measure of iron availability at the cellular level." (PMID 35075211, 2022). "Iron deficiency was defined by soluble transferrin receptor levels > 28.1 nmol/L and baseline anemia by hemoglobin levels < 130 g/L for men and < 120 g/L for women." (PMID 34533774, 2022). "In another study, a suboptimal environment of iron-deficiency in tumors was found to increase NHE9-mediated transferrin receptor surface recycling in a model of the blood–brain barrier." (PMID 35387234, 2022). "To assess the effects of cancer‐induced iron deficiency on skeletal muscle metabolism, we analyzed the transcript levels of the main cellular iron importer, transferrin receptor 1 (TFR1) in a cohort of cancer patients presenting body weight loss and anemia." (PMID 35199910, 2022). "Animal modeling of iron deficiency and defects in the transferrin receptor have been associated with neural tube and cardiovascular defects in animal models." (PMID 35979646, 2022). "The transferrin receptor is cleaved from the plasma membrane, and its plasma soluble form (sTfR) serves as a marker of iron deficiency." (PMID 34902367, 2022). "Under iron deficiency, it exhibits RNA-binding activity, which results in the stabilization of transferrin receptor 1 (TfR1) mRNA and the translational arrest of the mRNAs encoding ferritin and ferroportin." (PMID 36142654, 2022). "A national micronutrient survey in Ethiopia reported that iron deficiency anemia (IDA) accounts for 35% of anemia cases (using sTfR (soluble serum transferrin receptor)." (PMID 34996515, 2022). "In infants, several clinically used iron status parameters such as ferritin, soluble transferrin receptor, transferrin saturation, and zinc protoporphyrin were poor predictors of iron deficiency." (PMID 36425471, 2022). "While an abnormal serum ferritin level indicates iron storage disorder, both transferrin and soluble transferrin receptor (sTfR) tests are used to diagnose iron-deficiency anaemia or overload." (PMID 36140091, 2022). "Previous studies have suggested that ferritin, soluble transferrin receptor, transferrin saturation, and zinc protoporphyrin were poor predictors of iron deficiency in children." (PMID 36425471, 2022). "Elevated soluble transferrin receptor (sTfR) diagnostic of iron deficiency and linked with erythropoiesis has also been used in population studies on the assumption that sTfR is not influenced by inflammation." (PMID 36079755, 2022). "In this study, we show a location-specific mucosal transcriptional response to inflammation and iron deficiency of HIF1α-target genes (particularly of TFRC) in intestinal mucosa of patients with IBD." (PMID 35755436, 2022). "Recent studies in acute as well as chronic HF have linked lower levels of serum hepcidin and elevated soluble transferrin receptor (sTfR), a marker of both functional iron deficiency and erythroid activity, with higher levels of NT-proBNP." (PMID 36451923, 2022). "TFRC mRNA is degraded when cellular iron is sufficient, and stabilized as a result of cellular iron deficiency." (PMID 34556786, 2021).